JAK2 (Janus kinase 2)
Description:
Non-membrane spanning protein tyrosine kinase that phosphorylates type I receptors such as growth hormone (GHR), prolactin (PRLR), leptin (LEPR), erythropoietin (EPOR), thrombopoietin receptor (MPL/TPOR); or type II receptors including IFN-alpha, IFN-beta, IFN-gamma and multiple interleukins. Functionnally, plays a pivotal role in signal transduction and is involved in various processes such as cell growth, development, differentiation or histone modifications. Mediates essential signaling events in both innate and adaptive immunity. Mechanistically, following ligand-binding to cell surface receptors, phosphorylates specific tyrosine residues on the cytoplasmic tails of the receptor, creating docking sites for STATs proteins. Subsequently, phosphorylates the STATs proteins once they are recruited to the receptor. Phosphorylated STATs then form homodimer or heterodimers and translocate to the nucleus to activate gene transcription. For example, cell stimulation with erythropoietin (EPO) during erythropoiesis leads to JAK2 autophosphorylation, activation, and its association with erythropoietin receptor (EPOR) that becomes phosphorylated in its cytoplasmic domain. Then, STAT5 (STAT5A or STAT5B) is recruited, phosphorylated and activated by JAK2. Once activated, dimerized STAT5 translocates into the nucleus and promotes the transcription of several essential genes involved in the modulation of erythropoiesis. Part of a signaling cascade that is activated by increased cellular retinol and that leads to the activation of STAT5 (STAT5A or STAT5B). In addition, JAK2 mediates angiotensin-2-induced ARHGEF1 phosphorylation. Plays a role in cell cycle by phosphorylating CDKN1B. Cooperates with TEC through reciprocal phosphorylation to mediate cytokine-driven activation of FOS transcription. In the nucleus, plays a key role in chromatin by specifically mediating phosphorylation of 'Tyr-41' of histone H3 (H3Y41ph), a specific tag that promotes exclusion of CBX5 (HP1 alpha) from chromatin. Up-regulates the potassium voltage-gated channel activity of KCNA3. Binding of CNTF or the CLCF1/CLF heterodimer to CNTFR leads to IL6ST/gp130-LIFR dimerization followed by activation of JAK1 and JAK2 which in turns phosphorylate IL6ST/gp130 and LIFR. The tyrosine phosphorylated signaling receptors serve in turn as docking proteins for STAT3. Involved in the oncostatin-M-mediated signaling pathway through both type I OSM receptor complex (heterodimers composed of LIFR and IL6ST) and type II OSM receptor complex (heterodimers composed of OSMR and IL6ST).
Synonyms: JTK10
Tractability: Small molecule: an approved drug acts on it; a structure with a bound ligand is known; a high-quality ligand is known; it has a high-quality binding pocket; it belongs to a druggable protein family. Antibody: its Gene Ontology location is reachable by antibodies, with high confidence; UniProt places it where antibodies can reach, with medium confidence. PROTAC: it is named in the literature on targeted protein degradation; UniProt records ubiquitination sites on it; ubiquitination databases record sites on it; its protein half-life has been measured; a small molecule that binds it is known.
Target class: TK protein kinase group; Enzyme; Kinase; Protein Kinase; Tyrosine protein kinase JakA family
Chemical probes: AZ-960 (high quality), BARICITINIB, BMS-911543 (high quality), CHEMBL2178804, GANDOTINIB (high quality), PD080825, PD081063, PD081341, PD082222, PD082267, PD082411, PD082718, PD082734, PD083326, PD083340, PD083444, PD083796, PD083863, PD083865, PD084141, and 22 more
Safety:
Unwanted effects reported when the protein is acted on. In parentheses: how it was acted on, where the effect was seen, and who reports it.
heart disease (cardiovascular system; source: Force et al. (2011))
Gene: Protein-coding gene on chromosome 9 (4,984,390 to 5,129,948, forward strand). Ensembl gene ENSG00000096968.
Subcellular location: Endomembrane system; Cytoplasm; Nucleus
Subcellular location (Human Protein Atlas): Nucleoplasm; Focal adhesion sites; Plasma membrane
Pathways (Reactome):
Immune System: Growth hormone receptor signaling; IFNG signaling activates MAPKs; IL-6-type cytokine receptor ligand interactions; Inactivation of CSF3 (G-CSF) signaling; Interferon gamma signaling; Interleukin receptor SHC signaling; Interleukin-12 signaling; Interleukin-20 family signaling; Interleukin-23 signaling; Interleukin-27 signaling; Interleukin-3, Interleukin-5 and GM-CSF signaling; Interleukin-35 Signalling; Interleukin-4 and Interleukin-13 signaling; Interleukin-6 signaling; Prolactin receptor signaling; Regulation of IFNG signaling; Signaling by CSF3 (G-CSF)
Signal Transduction: Erythropoietin activates Phosphoinositide-3-kinase (PI3K); Erythropoietin activates Phospholipase C gamma (PLCG); Erythropoietin activates RAS; Erythropoietin activates STAT5; MAPK1 (ERK2) activation; MAPK3 (ERK1) activation; RAF activation; RAF/MAP kinase cascade; Signaling by Erythropoietin; Signaling by Leptin; Signaling by SCF-KIT
Disease: Paradoxical activation of RAF signaling by kinase inactive BRAF; Potential therapeutics for SARS; Signaling by BRAF and RAF1 fusions; Signaling by RAF1 mutants; Signaling by moderate kinase activity BRAF mutants; Signaling by phosphorylated juxtamembrane, extracellular and kinase domain KIT mutants; Signaling downstream of RAS mutants
Cell Cycle: Cyclin D associated events in G1
Cell-Cell communication: Activation of STAT3 by cadherin engagement
Chromatin organization: RMTs methylate histone arginines
Hemostasis: Factors involved in megakaryocyte development and platelet production
Gene Ontology:
Molecular function: heme binding; histone H3Y41 kinase activity; identical protein binding; non-membrane spanning protein tyrosine kinase activity; protein binding; protein kinase binding; protein tyrosine kinase activity; SH2 domain binding; signaling receptor binding; growth hormone receptor binding; interleukin-12 receptor binding; protein kinase activity; signaling receptor activator activity; acetylcholine receptor binding; ATP binding; histone binding; insulin receptor substrate binding; peptide hormone receptor binding; phosphatidylinositol 3-kinase binding; type 1 angiotensin receptor binding
Biological process: cell adhesion; cell surface receptor signaling pathway via JAK-STAT; ciliary neurotrophic factor-mediated signaling pathway; collagen-activated signaling pathway; cytokine-mediated signaling pathway; erythropoietin-mediated signaling pathway; granulocyte-macrophage colony-stimulating factor signaling pathway; growth hormone receptor signaling pathway; growth hormone receptor signaling pathway via JAK-STAT; interleukin-12-mediated signaling pathway; interleukin-23-mediated signaling pathway; interleukin-3-mediated signaling pathway; interleukin-5-mediated signaling pathway; leukemia inhibitory factor signaling pathway; negative regulation of protein localization to chromatin; oncostatin-M-mediated signaling pathway; positive regulation of cell-substrate adhesion; positive regulation of leukocyte proliferation; positive regulation of platelet activation; positive regulation of platelet aggregation; positive regulation of SMAD protein signal transduction; post-translational protein modification; regulation of inflammatory response; response to antibiotic; response to interleukin-12; and 68 more
Cellular component: chromatin; cytoplasm; cytoplasmic side of plasma membrane; extrinsic component of cytoplasmic side of plasma membrane; extrinsic component of plasma membrane; granulocyte macrophage colony-stimulating factor receptor complex; nucleoplasm; nucleus; caveola; cytosol; endosome lumen; interleukin-5 receptor complex; membrane raft; plasma membrane; endomembrane system; endosome; euchromatin; glutamatergic synapse; membrane; postsynapse
Genetic constraint (gnomAD): Loss-of-function variants: 29 observed, 46.64 expected, observed/expected ratio (o/e) 0.62, 90% interval 0.46 to 0.85. The upper end of that interval is the gene's LOEUF score, 0.85, which puts it in group 3 of 6, group 1 being the genes least tolerant of losing a copy. Missense variants: 568 observed, 566.05 expected, observed/expected ratio (o/e) 1, 90% interval 0.94 to 1.08. Synonymous variants: 200 observed, 186.19 expected, observed/expected ratio (o/e) 1.07, 90% interval 0.96 to 1.21.
Cancer hallmarks: escaping programmed cell death (promotes); proliferative signalling (promotes); change of cellular energetics (promotes); tumour promoting inflammation (promotes)
Homologues: Orthologues: macaque JAK2 (98% identical), rabbit JAK2 (95% identical), pig JAK2 (95% identical), chimpanzee JAK2 (95% identical), rat Jak2 (95% identical), mouse Jak2 (94% identical), dog JAK2 (89% identical), guinea pig JAK2 (86% identical), tropical clawed frog jak2 (78% identical), zebrafish jak2b (68% identical), zebrafish jak2a (64% identical). Paralogues in human: JAK3 (49% identical), JAK1 (43% identical), TYK2 (39% identical), HCK (15% identical), LYN (15% identical), LCK (15% identical), FRK (15% identical), ABL1 (14% identical), BLK (14% identical), FYN (14% identical), PTK2 (14% identical), SYK (14% identical), and 20 more.
Diseases named in the same sentence as JAK2 in open-access papers:
JAK2 is named in the same sentence as 648 diseases in open-access papers, as found by Europe PMC text mining. Sharing a sentence is not in itself a finding about the gene and the disease. The quoted sentences say what the papers report.
myeloproliferative neoplasm (730 papers, 2006 to 2026). A clonal hematopoietic stem cell disorder, characterized by proliferation in the bone marrow of one or more of the myeloid (i.e., granulocytic, erythroid, megakaryocytic, and mast cell) lineages. "Essential thrombocytosis (ET) is a myeloproliferative neoplasms (MPNs) primarily caused by JAK2 gene mutations." (PMID 41560006, 2026). "Polycythemia vera (PV) is a myeloproliferative neoplasm characterized by the clonal expansion of hematopoietic stem cells, commonly caused by pathogenic variants in Janus kinase 2 (JAK2)." (PMID 42211688, 2026). "Polycythemia vera (PV) is a JAK2-mutated myeloproliferative neoplasm associated with thrombotic and vascular complications." (PMID 42117004, 2026). "Polycythemia vera (PV) is one of the most prevalent myeloproliferative neoplasms (MPNs), identified by the presence of activating somatic mutations in the JAK2 gene and characterized by excessive production of red blood cells, platelets, and neutrophils." (PMID 40087986, 2025). "The JAK2 46/1 haplotype has emerged as a significant germline genetic factor that predisposes individuals to myeloproliferative neoplasms (MPNs), particularly through its strong association with the acquisition of the JAK2 V617F somatic mutation." (PMID 41226376, 2025). "Mutations in the JAK2 gene are associated with myeloproliferative neoplasms (MPNs) such as polycythemia vera (PV) and essential thrombocythemia (ET), while aberrant JAK2 activity is also associated with a number of immune diseases." (PMID 40332385, 2025). "Mutations such as JAK2 V617F, while more commonly associated with myeloproliferative neoplasms, have also been implicated in pediatric leukemia subtypes, including acute lymphoblastic leukemia and acute myeloid leukemia." (PMID 40486651, 2025). "Polycythemia vera (PV) is a chronic myeloproliferative neoplasm characterized by increased erythrocytes and commonly associated with JAK2 mutations." (PMID 41321895, 2025). "The expression and mutation of JAK2 is associated with glucose metabolic reprogramming in myeloproliferative neoplasms, type 3 diabetes‐induced liver tumors and mesenchymal stem cells, and the JAK2/Stat3 pathway facilitates the progression of HCC." (PMID 40693878, 2025). "Myeloproliferative neoplasms (MPN) often carry the gain-of-function mutation V617F of the Janus kinase 2 (JAK2), which leads to a constitutive activation of the downstream signaling cascade." (PMID 40725184, 2025). "Consistently, the French Intergroup on Myeloproliferative Neoplasms (FIM) reported a decrease in the JAK2 allele burden of more than 50% in more than half of the patients, while the CALR remained stable." (PMID 41463191, 2025). "Myelofibrosis (MF) is a myeloproliferative neoplasm that is accompanied by driver JAK2, CALR, or MPL mutations in more than 90% of cases, leading to constitutive activation of the JAK–STAT pathway." (PMID 40062529, 2025). "In chronic myeloproliferative disorders with Bcr-Abl negativity, the JAK2 gene mutation is the most common mutation (accounting for 95% of PV cases, 60% of ET cases, and 50% of PMF cases)." (PMID 40572650, 2025). "Six patients had mutations in driver genes of myeloproliferative neoplasms (MPNs) (JAK2 n = 5 (4%), CALR n = 1 (1%))." (PMID 41008838, 2025). "Polycythemia vera, also known as Vaquez disease, is a myeloproliferative neoplasm characterized by the overproduction of red blood cells due to a mutation in the JAK2 gene." (PMID 40932623, 2025). "One of the most well-documented gain-of-function (GOF) mutations in the JAK-STAT pathway is JAK2-V617F, which is prevalent in myeloproliferative neoplasms (MPNs) including polycythemia vera, essential thrombocythemia, and primary myelofibrosis." (PMID 40140631, 2025). "In myeloproliferative neoplasms with JAK2 mutations, such as essential thrombocythemia and myelofibrosis, the risk of thrombosis increases up to sixfold." (PMID 40443500, 2025).
myeloproliferative neoplasm (continued). "Specifically, the somatic V617F mutation in the pseudokinase domain of JAK2 is recognized as a major driver mutation in many chronic myeloproliferative neoplasms." (PMID 40519492, 2025). "Polycythemia vera (PV) is a JAK2‐mutated myeloproliferative neoplasm characterized by clonal erythrocytosis." (PMID 41321895, 2025). "Polycythemia vera (PV) is a chronic malignancy classified within the group of Janus kinase 2 (JAK2) mutation-driven myeloproliferative neoplasms." (PMID 41091181, 2025). "In patient 2, prominent megakaryocytic hyperplasia and dysplasia hinted at the possibility of evolution from an underlying JAK2-mutated myeloproliferative neoplasm (MPN)." (PMID 41408008, 2025). "The limited research conducted in Jak2-mutant mouse models has uncovered intriguing roles of immune cells, like macrophages, in CVD and has examined the connection between CVD and myeloproliferative neoplasms (MPNs) induced by Jak2 mutations." (PMID 39744945, 2025). "Although JAK2 mutations are commonly associated with adult hematological cancers like myeloproliferative neoplasms, there is growing evidence that JAK2 also plays a role in pediatric leukemia, including ALL and AML." (PMID 40486651, 2025). "Current treatment goals for polycythemia vera, a myeloproliferative neoplasm characterized by JAK2 mutations, are mainly to prevent thrombosis." (PMID 40087986, 2025). "Polycythemia vera (PV) is a myeloproliferative neoplasm associated with a haematocrit over 45% and a JAK2 mutation (mainly V617F), with phlebotomy being the commonest treatment to lower the haematocrit in lower-risk patients." (PMID 39942772, 2025). "Essential thrombocythemia (ET), a myeloproliferative neoplasm frequently driven by JAK2 V617F mutations, results in thrombocytosis and hypercoagulability, elevating the risk of bleeding and thrombotic events including ischemic stroke." (PMID 40926892, 2025). "Although JAK2 V617F mutations are more commonly associated with myeloproliferative disorders such as polycythemia vera and essential thrombocythemia in adults, its role in pediatric leukemia has been increasingly recognized." (PMID 40486651, 2025). "In the pathological context of myeloproliferative disorders, such as polycythemia vera, a gain‐of‐function mutation in the JAK2 gene is often the underlying cause." (PMID 40952332, 2025). "Mutations in JAK2 have been associated with myeloproliferative disorders, which can have secondary effects on muscle function." (PMID 40264040, 2025). "When a myeloproliferative disease is diagnosed, JAK2 is one of the first diagnostic indicators to be examined." (PMID 39129166, 2025). "Gain-of-function (GOF) mutations in JAK1 and JAK3 are associated with leukaemia and lymphoma, while GOF mutations in JAK2 are highly associated with myeloproliferative disease including polycythemia vera, essential thrombocytopenia, and primary myelofibrosis." (PMID 40333091, 2025). "Initial molecular testing for common mutations including JAK2 (V617F, exon 12, exon 13 mutations) yielded normal results, reducing the likelihood of polycythemia vera and other acquired myeloproliferative disorders, though rare variants cannot be excluded." (PMID 40627222, 2025). "For the treatment of JAK2‐mutated patients with myeloproliferative diseases, the drug inhibition of JAK2 with ruxolitinib, fedratinib and momelotinib is used." (PMID 40952332, 2025). "Other genetic findings included two pathogenic variants associated with atopic dermatitis (FLG, C0120), a VUS for familial Mediterranean fever (MEFV, C037) and one somatic pathogenic variant for myeloproliferative disorder (JAK2, C123)." (PMID 40455168, 2025). "Primary myelofibrosis is a clonal myeloproliferative disorder characterized by fibrous tissue deposits in the bone marrow, commonly associated with JAK2, CALR, or MPL mutations." (PMID 39807111, 2025).